PTH (parathyroid hormone)
Diseases named in the same sentence as PTH in open-access papers (continued):
Sharing a sentence is not in itself a finding about the gene and the disease.
depression (continued). "Analysis was done to diagnose anxiety and depression based on the HADS scores in patients with PTH levels above 400 pg/ml and those with PTH levels below 400 pg/ml." (PMID 38681457, 2024). "Studies have shown that PTH can activate PTH2 receptors, which have been linked to areas in the brain that are relevant for anxiety and depression in animal studies." (PMID 37450218, 2023). "Age, monthly income, feeling of pain, worried about being infected by COVID-19, vascular access of dialysis, blood phosphorus, PTH, and Hb are the factors related to developing anxiety and depression in the MHD patients." (PMID 37046867, 2023). "Studies have shown that there are many factors associated with sleep disturbance in MHD patients, such as gender, diet, depression and serum PTH levels." (PMID 35959399, 2022). "The mean PTH values in participants with severe (15.4 ± 18.6) depression were also higher than those in participants with normal (5.55 ± 2.17), mild (5.89 ± 2.45), and moderate (6.19 ± 3.23) depression." (PMID 35458111, 2022). "At last, it is also possible that PTH levels contribute to the relation between vitamin D, BMI, and depression." (PMID 34847921, 2021). "This patient was a 61-year-old male displaying clinical signs of depression as well as elevated serum calcium and plasma PTH levels." (PMID 32193823, 2020). "Maintaining optimal PTH levels plays a crucial role in mitigating anxiety and depression." (PMID 38681457, 2024). "Our study suggests that maintaining optimal PTH levels may play a crucial role in mitigating anxiety and depression among hemodialysis patients." (PMID 38681457, 2024). "Analysis of depression among MHD patients with laboratory tests showed that age, duration of dialysis, vascular access of dialysis, feeling of pain, worried about being infected by COVID-19, Hb, PTH, and P were the factors that influenced depression (all p < 0.05)." (PMID 37046867, 2023). "They wanted to test the correlation between PTH levels and depression in dialysis patients." (PMID 37425517, 2023). "Studies have suggested that PTH may play a role in the pathogenesis of depression, and vitamin D status could be a direct or indirect intermediating factor." (PMID 35458111, 2022). "Serum levels of OCN and cortisol, rather than PTH and calcium, are associated with the development of anxiety and depression symptoms in PHPT patients." (PMID 34456863, 2021). "However, it is noteworthy that there is evidence of a negative association between PTH and depression." (PMID 32848932, 2020). "Conversely, patients on hemodialysis with low PTH levels show a high proportion of normal HADS scores for anxiety and depression." (PMID 38681457, 2024). "Patients with PTH levels >400 pg/ml exhibited higher rates of abnormal HADS scores for anxiety and depression than those with PTH levels <400 pg/ml." (PMID 38681457, 2024). "Monthly laboratory records for parathyroid hormone (PTH) levels and the Hospital Anxiety and Depression Scale (HADS) for mental health assessment were utilized." (PMID 38681457, 2024). "Depression being a major prevalent neuropsychiatric symptom these days, we tried to find a relation between MDD and increased PTH levels." (PMID 37425517, 2023). "Data from LASA and the Netherlands Study of Depression and Anxiety (NESDA) were used to calculate assay specific parathyroid hormone (PTH) reference levels in relation to 25-hydroxyvitamin D (25-OHD) levels." (PMID 27544533, 2016). "First, six infusions of ketamine associated with increased the levels of leptin and OPG, and decreased the levels of OC, OPN, SOST, PTH and FGF23 in patients with depression, which occurred immediately the day after the last infusion (Day 13) and lasted for 2-week post-infusion (Day 26)." (PMID 38287453, 2024). "In our study, we also assessed the relationship between PTH levels and depression, since studies postulate that PTH serum levels are higher in hemodialysis patients with depression compared to those without depression." (PMID 38255209, 2024).
depression (continued). "In this study, we found an increase in plasma levels of leptin and OPG, and a decrease in levels of OC, OPN, SOST, PTH and FGF23 after six ketamine infusions in adults with depression, indicating that ketamine may mediate a beneficial effect on BMD." (PMID 38287453, 2024). "The study had included 3369 men, aged between 49 to 71 years, that were taking part in the European Male Ageing Study, depression was evaluated using the Beck Depression Inventory-II (BDI-II), and radioimmunoassay was used to assess serum 25(OH)D and parathyroid hormone (PTH) levels." (PMID 35637805, 2022). "Thus, investigating the relative contribution of PTH, calcium, OCN, and cortisol to the development of anxiety and depression behaviors in PHPT in a larger cohort, especially before and after parathyroidectomy, is very important." (PMID 34456863, 2021). "In patients with depression, the conversion of tryptophan in the brain stops due to disregulation of parathyroid hormone, which produces little or no serotonin, further contributes to a defective mental state, changed cognition, and false sensory gait." (PMID 34667146, 2021). "Moreover, older hemodialysis patients with elevated PTH levels exhibit a high prevalence of depression in many studies, indicating a negative impact on various aspects of their well-being." (PMID 38681457, 2024). "They assessed depression symptoms by kidney disease quality of life (KDQOL) form in 10 patients who had intact PTH values above 1000 pg/mL and in a control group of 10 patients who had PTH values less than 400 pg/mL and were going through dialysis for various diseases." (PMID 37425517, 2023). "In conclusion, this study showed that the prevalence of self-assessed symptoms of depression in chronic hemodialysis patients with end-stage kidney disease is not related to the levels of plasma BDNF, NfL, and PTH." (PMID 38255209, 2024).
postmenopausal osteoporosis (39 papers, 2008 to 2025). Metabolic disorder associated with fractures of the femoral neck, vertebrae, and distal forearm. "TPTD is a commercially available recombinant PTH fragment 1–34 for the treatment of postmenopausal osteoporosis and high risk of imminent fractures." (PMID 40894392, 2025). "Teriparatide, or recombinant human parathyroid hormone, is recognized for its robust osteogenic properties and is extensively utilized in treating postmenopausal osteoporosis." (PMID 40176894, 2025). "PTH is a hormone that regulates calcium and phosphorus metabolism, and 15.6% of postmenopausal osteoporosis patients had elevated PTH." (PMID 41030850, 2025). "TPT consists of the biologically active N-terminal 34 amino acids of human parathyroid hormone (PTH) and is approved in the USA for the treatment of postmenopausal osteoporosis in patients at high risk of bone fracture." (PMID 41445733, 2025). "The administration of parathyroid hormone (PTH) has been demonstrated to enhance bone mineral density (BMD) in estrogen‐deficient women, thereby reducing the risk of fractures in those with postmenopausal osteoporosis." (PMID 40620511, 2025). "To examine the effects of PTH and propranolol on systemic bone loss after osteoporotic fracture, we generated tibia fracture models in mice with ovariectomy (OVX)-induced postmenopausal osteoporosis." (PMID 38514644, 2024). "Even before postmenopausal osteoporosis was described, in the 1930s, the young intact rat was the model used to first show anabolic (bone-building) properties of parathyroid hormone (PTH), forming the basis of teriparatide therapy." (PMID 38315213, 2024). "Pharmacologic therapies for postmenopausal osteoporosis encompass a range of treatments like bisphosphonates, SERMs, calcitonin, PTH analogues, RANK ligand inhibitors, and hormone replacement therapy." (PMID 38970109, 2024). "The recombinant parathyroid hormone (PTH) is the only therapy for postmenopausal osteoporosis that increase bone mass." (PMID 34740382, 2021). "Several previous studies on denosumab in postmenopausal osteoporosis have also shown the temporary increases in plasma PTH after the injection." (PMID 33112830, 2020). "The results of this study show the possible role of allelic combinations of SOST rs1234612, PTH rs7125774, FDPS rs2297480, and GGPS1 rs10925503 gene variants in the individual response to BPs treatment in women with postmenopausal osteoporosis." (PMID 31437227, 2019). "Teriparatide, a recombinant form of parathyroid hormone (PTH) used to treat postmenopausal osteoporosis, was prescribed for 12 months and normalized serum calcium levels." (PMID 31372586, 2019). "In the last decade, the parathyroid hormone (PTH) has become more important as a possible alternative for the treatment of postmenopausal osteoporosis." (PMID 21603135, 2011). "Numerous agents for the prevention and/or treatment of postmenopausal osteoporosis are currently available, including bisphosphonates, estrogen therapy, parathyroid hormone (PTH), calcitonin, and the selective estrogen receptor modulator (SERM) raloxifene." (PMID 20569451, 2010). "PTH is a bone anabolic agent and effective treatment for postmenopausal osteoporosis, maybe by its effect of increase Wnt10b production in osteoblasts." (PMID 33013696, 2020). "Intermittent PTH is an effective bone anabolic treatment regimen for postmenopausal osteoporosis." (PMID 24637846, 2014). "This study aimed to investigate the effect of electromagnetic field (EMF) combined with recombinant human parathyroid hormone (rhPTH) on bone mineral density (BMD) and bone turnover indicators in postmenopausal osteoporosis (PMOP) patients." (PMID 39985668, 2025). "Teriparatide, a recombinant fragment of human parathyroid hormone (PTH 1-34), is the sole anabolic agent approved for treating postmenopausal osteoporosis." (PMID 22967310, 2012).
postmenopausal osteoporosis (continued). "Other studies have found that the cause of postmenopausal osteoporosis was the abnormal activation of osteoclasts, and as the osteogenic drug PTH cannot alleviate osteolysis, it was not suitable for the treatment of postmenopausal osteoporosis." (PMID 33820875, 2021).
type 2 diabetes (38 papers, 2009 to 2025). "Inverse associations were evident between the HbA1c, 25(OH)D and PTH levels in Korean patients with type 2 diabetes." (PMID 27362844, 2016). "Inverse associations were evident between HbA1c, 25(OH)D and PTH levels in Korean patients with type 2 diabetes." (PMID 27362844, 2016). "Therefore, we sought independent associations between 25(OH)D, PTH, and HbA1c levels in Korean patients with type 2 diabetes." (PMID 27362844, 2016). "Likewise, high levels of PTH were associated with a significantly increased risk for premature mortality in women with type 2 diabetes." (PMID 26078787, 2015). "While bone turnover markers were not available in this case, referenced studies report that both GIP and GLP-1 receptor agonists can stimulate parathyroid hormone (PTH) secretion in individuals with type 2 diabetes." (PMID 40911613, 2025). "In rats with type 2 diabetes and a femoral fracture the administration of PTH resulted in increased bone formation, mineralization and mechanical strength." (PMID 34458509, 2021). "In conclusion, inverse associations were evident between hemoglobin A1c, 25-hydroxyvitamin D and parathyroid hormone levels in Korean patients with type 2 diabetes." (PMID 27362844, 2016). "We aimed to prospectively study relationships between serum 25-OH vitamin D3 (vitamin D) and of serum parathyroid hormone (PTH) to total mortality in type 2 diabetes." (PMID 26078787, 2015). "In contrast to earlier reports on relationships between vitamin D and mortality in patients with type 2 diabetes, our analysis also incorporated data on corrected calcium and of serum PTH levels." (PMID 26078787, 2015). "We herein report a study of 698 patients with type 2 diabetes with a median follow-up of six years in which serum levels of vitamin D, calcium and PTH were analyzed." (PMID 26078787, 2015). "Our observational data in patients with type 2 diabetes show that the finding of low vitamin D levels in men or of high PTH levels in women gives independent prognostic information of an increased risk for total mortality." (PMID 26078787, 2015). "The mean serum levels of 25-hydroxyvitamin D (25(OH) D) and PTH were 53.41 ± 33.25 nmol/l and 40.24 ± 18.24 pmol/l, respectively, in type 2 diabetic patients." (PMID 24398023, 2014). "In insulin resistant and in type 2 diabetic rats, the occurrence of an insulin- and PTH-independent bone anabolic action mediated by GLP-1 has been demonstrated, together with an osteogenic action on altered bone structure on osteoblasts." (PMID 23785355, 2013). "Both PTH (OR 0.934, 95% CI 0.878–0.994, P = 0.076) and 25(OH)D more than 20 ng/ml (OR 0.285, 95% CI 0.055–1.472, P = 0.134) was not statistically significantly correlated under the influence of multiple factors in type 2 diabetes with HT." (PMID 35804367, 2022). "Furthermore, it has been demonstrated that type 2 diabetics presented higher serum PTH-rP levels than control subjects, and PTH-rP induces insulin expression in pancreatic β-cells." (PMID 34441291, 2021). "Among 368 type 2 diabetes, 70 (59.8%) had an elevated PTH level." (PMID 29190676, 2017). "We evaluated associations between 25-hydroxyvitamin D, parathyroid hormone, and hemoglobin A1c levels after adjusting for other covariates, including log transformed 25-hydroxyvitamin D levels and log transformed parathyroid hormone levels, in Korean patients with type 2 diabetes." (PMID 27362844, 2016). "In addition to type 2 diabetes and age, both PTH and serum phosphate had significant direct effects on MS; 0.36 (95% Credibility Interval (CrI) [0.15, 0.57]) and 0.28 (95% CrI [0.10,0.47]), respectively." (PMID 21306649, 2011). "The apparent paradoxically low mean serum PTH concentration in patients with both MS and type 2 diabetes could be partly explained by the concomitant low magnesium level, as low serum magnesium is known to inhibit PTH secretion." (PMID 19187564, 2009).
type 2 diabetes (continued). "The aims of this study is to observe the levels of serum 25-hydroxyvitaminD (25OHD), parathyroid hormone and bone mineral density (BMD) in type 2 diabetes as well as to analyze the correlationship between 25OHD level and BMD." (PMID 29190676, 2017). "We also found effect modification by eGFR for the cross-sectional association between PTH and BNP (P<0.001) but not by prior CVD (P=0.151) or by the presence of type 2 diabetes (P=0.171)." (PMID 23781303, 2012). "Patients with MS but not type 2 diabetes had significantly higher PTH concentrations than patients without MS, whereas patients with both MS and type 2 diabetes had significantly lower serum magnesium concentrations than those without MS." (PMID 19187564, 2009). "Interestingly, another study reported that low 25(OH) D was associated with an increased risk of cardiovascular morbidity and mortality in people with type 2 diabetes independent of PTH." (PMID 29437901, 2018). "However, our data cannot discern whether this relationship was based on mildly elevated PTH levels due to relative lack of active vitamin D, but it does suggest that measurement of serum PTH can add information in the clinical evaluation of risk for mortality in women with type 2 diabetes." (PMID 26078787, 2015).
endothelial dysfunction (37 papers, 2012 to 2025). In vascular diseases, endothelial dysfunction is a systemic pathological state of the endothelium (the inner lining of blood vessels) and can be broadly defined as an imbalance between vasodilating and vasoconstricting substances produced by (or acting on) the endothelium. "Research has demonstrated that PTH is associated with various cardiovascular diseases, including endothelial dysfunction, vascular stiffness, calcification, and reduced elasticity of large arteries." (PMID 38609861, 2024). "Among CKD patients, biomarkers involved in the pathogenesis of CKD-mineral bone disorder (CKD-MBD), such as phosphorus, parathyroid hormone, and fibroblast growth factor 23, are associated with endothelial dysfunction." (PMID 35903313, 2022). "BP increasing the effect of PTH except in regulating the 25-OH vitamin D level can be due to increasing renin release from the kidney, causing endothelial dysfunction, increasing arterial stiffness, and activating the sympathetic system." (PMID 34946242, 2021). "Altogether, our data represent the first direct evidence that PTH causes endothelial dysfunction in a ROS-dependent manner, through a surge of mitochondrial Ca2+." (PMID 30662585, 2018). "The present study was designed to verify in vitro the ability of sustained exposure to PTH to cause endothelial dysfunction, exploring the underlying mechanisms." (PMID 30662585, 2018). "The present study was designed to verify in vitro the ability of sustained exposure to PTH to cause endothelial dysfunction, with a particular focus on the potential role of oxidative stress." (PMID 30662585, 2018). "However, direct evidence of PTH-induced endothelial dysfunction is missing, as well as the understanding of the underlying mechanisms." (PMID 30662585, 2018). "Indeed, PTH has been directly implicated in a wide range of vascular alterations, such as endothelial dysfunction, vascular calcification, and vascular remodeling, which lead to atherogenesis and arterial stiffness." (PMID 30662585, 2018). "PTH stimulates vascular smooth muscle cells to produce factors involved in sclerosis, and induces the endothelial expression of factors implicated in endothelial dysfunction, such as endothelin-1 and interleukin-6." (PMID 22937036, 2012). "Besides, PTH per se has been implicated in directly causing endothelial dysfunction." (PMID 32129057, 2020). "The consequences of 25[OH]D deficiency and elevated PTH levels are calcium loading, with cardiomyocyte and skeletal muscle contractile dysfunction, cellular hypertrophy, oxidative stress, immune activation, endothelial dysfunction (including enhanced endothelin-1 release)." (PMID 30121806, 2019). "Therefore, we investigated whether PTH caused endothelial dysfunction through an increase in ROS production." (PMID 30662585, 2018). "Given the potential role of PTH in modulating cardiovascular physiology, a critical gap remains in knowledge regarding the molecular effects of PTH on platelet activation, endothelial dysfunction, and oxidative stress in individuals with chronic HypoPT." (PMID 41109132, 2025). "The aim of this study was to compare biomarkers of endothelial dysfunction, 25-hydroxyvitamin D (25(OH)D), intact parathyroid hormone (iPTH), miRNA 155, and miRNA 145, in patients with CKD versus controls." (PMID 39246913, 2024). "Another study probed into the role of PTH in endothelial dysfunction and found that PTH increased ROS and mediated oxidative stress to impair endothelial angiogenic competence in vitro experiments." (PMID 37854190, 2023). "Among the candidate mechanisms able to induce endothelial dysfunction, we chose to investigate the role of ROS since the presence in literature of indirect evidence about the relation between PTH levels and markers of oxidative stress." (PMID 30662585, 2018). "To verify more complex phenotypes of PTH-induced endothelial dysfunction, we evaluated angiogenic responses in vitro." (PMID 30662585, 2018).